CFTR (CF transmembrane conductance regulator)
Diseases named in the same sentence as CFTR in open-access papers (continued):
Sharing a sentence is not in itself a finding about the gene and the disease.
cystic fibrosis (continued). "Several lines of evidence shown that in cystic fibrosis the lack of the cystic fibrosis transmembrane conductance regulator (CFTR) is accompanied by changes in the plasma membrane composition of a bioactive class of lipids known as sphingolipids." (PMID 37315117, 2023). "ALI cultures derived from cystic fibrosis ferret tracheal airway basal cells demonstrated a lack of CFTR-mediated currents and a significant increase in pulmonary ionocytes as assessed by the expression of transcription factors FOXI1 and ASCL3." (PMID 37730992, 2023). "CF is caused by the presence of pathogenic variants of the cystic fibrosis transmembrane conductance regulator (CFTR), which encodes a transmembrane protein consisting of 1480 amino acids and forms a cAMP-dependent chloride channel in the membranes of epithelial cells." (PMID 38203285, 2023). "The introduction of mutation-specific combination therapy with the cystic fibrosis transmembrane conductance regulator (CFTR) modulators elexacaftor/tezacaftor/ivacaftor (ELX/TEZ/IVA) has substantially improved lung function and quality of life of people with cystic fibrosis." (PMID 36154176, 2022). "The cystic fibrosis transmembrane conductance regulator (CFTR) potentiator ivacaftor, commonly used to treat cystic fibrosis patients, exerts apparent antimicrobial activity via weak inhibition of DNA gyrase and topoisomerase IV enzymes, owing to certain structural similarities with quinolones." (PMID 36558754, 2022). "In clinical trials, ataluren did not significantly improve lung disease in cystic fibrosis patients, for whom at least 30–35% of normal CFTR function is needed to alleviate pulmonary dysfunction." (PMID 35857082, 2022). "Whole exome sequencing data for the CFTR gene did not confirm a genetic diagnosis of cystic fibrosis in the proband." (PMID 34671974, 2022). "Finally, the cystic fibrosis-transmembrane conductance regulator (CFTR), an ion channel transporting chloride and bicarbonate across the apical surfaces of epithelia, is involved in cystic fibrosis." (PMID 36012639, 2022). "CTX increases the cystic fibrosis transmembrane conductance regulator (CFTR) chloride channel current and corrects ∆F508CFTR dysfunction, which could have an impact on cystic fibrosis." (PMID 36548772, 2022). "These organoids have facilitated the assessment of the cystic fibrosis transmembrane conductance regulator (CFTR) function in individual patients in vitro, and in turn the effect of different drugs used to treat cystic fibrosis, including VX-809 (lumacaftor) and VX-770 (ivacaftor)." (PMID 34147034, 2022). "In cystic fibrosis, an inhibition of ENaC through CFTR is absent, which leads to a decrease in airway surface liquid height and to dehydration of the airways." (PMID 35954259, 2022). "Furthermore, cells with F508del CFTR [a phenylalanine deletion common in cystic fibrosis patients] demonstrated a further reduction of ALOX15B expression when compared to the WT CFTR expression in CFBE41o− bronchial epithelial cells." (PMID 36438817, 2022). "These drugs treat the basic defect in cystic fibrosis by increasing CFTR function with improvement of lung function and quality of life, and may improve clinical outcomes also by correcting the dysregulated immune function that characterizes CF." (PMID 34943888, 2021). "Cystic fibrosis is an autosomal negative genetic disease characterized by a defect in the cystic fibrosis transmembrane conductance regulator (CFTR) protein." (PMID 35028178, 2021). "Cystic Fibrosis is a progressive autosomal recessive disease characterised by a dysfunction in a chloride channel, the membrane protein cystic fibrosis transmembrane conductance regulator (CFTR), resulting in thick and sticky mucus obstructing the airways, for instance." (PMID 34069415, 2021).
cystic fibrosis (continued). "Although CF is not specifically an inflammatory disease, the secretory defect due to the dysfunction of the cystic fibrosis transmembrane conductance regulator (CFTR) Cl- channel causes inflammation and fibrosis of the pancreas that can also affect the endocrine functions." (PMID 34566890, 2021). "Since patients with cystic fibrosis are prone to developing pancreatic problems, including pancreatitis, CFTR is a relevant candidate gene for pancreatitis in non-CF patients." (PMID 34768335, 2021). "There is continuous interest in studying CFTR molecular disease mechanisms as not all cystic fibrosis patients have a therapeutic option available." (PMID 34947992, 2021). "In Europe, around 20% of patients with cystic fibrosis are not currently eligible for CFTR modulators." (PMID 34685773, 2021). "In the view of such diverse mitochondrial function dysregulation in cystic fibrosis, the role of CFTR should not be neglected." (PMID 34832033, 2021). "Cystic fibrosis is a genetic disease characterized by the lack of cystic fibrosis transmembrane conductance regulator (CFTR) protein expressed in epithelial cells." (PMID 32098269, 2020). "CaCC was shown to be preserved or enhanced in human and murine cystic fibrosis airways as a mechanism to compensate for the lack of CFTR." (PMID 32676036, 2020). "Cystic fibrosis transmembrane conductance regulator (CFTR) is an ion channel, widelyexpressed in epithelial cells, mutation (mostly at position 508, DF508) of which causes agenetic disorder, cystic fibrosis that affects the lung, pancreas, liver, kidneys andintestine." (PMID 33501367, 2020). "Loss-of-function mutations in CFTR are associated with absence of the vas deferens and epididymis abnormalities in cystic fibrosis and abundant CFTR expression is seen in the genital duct epithelium of humans and many other species." (PMID 32855272, 2020). "The results turned out that CRCs from the cystic fibrosis mouse model CFTR ∆F508 failed to respond to forskolin, a CFTR activator, in 3D matrigel and transwell cultures." (PMID 32478897, 2020). "In CF, the lack of the expression of the cystic fibrosis transmembrane conductance regulator (CFTR) gene causes depletion of the periciliary liquid layer at the surface of the tracheal epithelium, which and inhibits clearance of the mucus coat from the lung, bronchial tree, and trachea." (PMID 32252376, 2020). "A novel feature of the model is the predictive capacity of lumen formation, a marker of baseline CFTR function that correlates with short-circuit current activation of CFTR in monolayers and discriminates the cystic fibrosis phenotype from non-CF." (PMID 32485957, 2020). "In particular, major cystic fibrosis transmembrane conductance regulator (CFTR) mutations and cystic fibrosis are absent in the former." (PMID 30956978, 2019). "Colocalizing with CFTR, SLC26A9 has been proposed as a target for the treatment of cystic fibrosis." (PMID 31339488, 2019). "Additionally, matured HIOs expressed functional cystic fibrosis transmembrane conductance regulator (CFTR) and were capable of swelling in response to forskolin, an assay designed to screen for Cystic Fibrosis therapeutic drugs." (PMID 31956653, 2019). "In cystic fibrosis, SNOs have been shown to increase expression of mutant CFTR in rats, and it’s possible that endogenous SNO production could become an effective treatment for children with cystic fibrosis." (PMID 29073241, 2017). "The dysfunction of CFTR often manifests as abnormal external secretion in the respiratory tract, digestive tract, urogenital tract and other epithelial tissues and can lead to diseases such as cystic fibrosis, secretory diarrhea, polycystic kidney disease (PKD), and infertility." (PMID 28445932, 2017). "Absence of a functional CFTR leads to chronic pulmonary inflammation, as seen in cystic fibrosis patients." (PMID 28439270, 2017).
cystic fibrosis (continued). "The CF diagnosis is based on neonatal screening findings and/or phenotypic manifestations, family history, and higher chloride ion (Cl−) concentration in sweat, in addition to two mutations in the CFTR gene (cystic fibrosis transmembrane conductance regulator) (OMIM: *602421)." (PMID 29124052, 2017). "Research is already underway on a number of PCs and PRs that might rescue cystic fibrosis transmembrane conductance regulator (CFTR), changes which lead to cystic fibrosis." (PMID 28662078, 2017). "It is not surprising then that defects in CFTR function are linked to disease, including life-threatening secretory diarrhoeas, such as cholera, as well as the inherited disease, cystic fibrosis, one of the most common life-limiting genetic diseases in Caucasian populations." (PMID 27714410, 2017). "Cystic Fibrosis is an autosomal recessive genetic disorder where the Cystic Fibrosis Transmembrane Conductance Regulator (CFTR) protein fails to conduct chloride ions at the apical surface of epithelia." (PMID 29872606, 2017). "Mutations in the Cystic Fibrosis Transmembrane Conductance Regulator (CFTR) gene affect CFTR protein biogenesis or its function as a chloride channel, resulting in dysregulation of epithelial fluid transport in the lung, pancreas and other organs in cystic fibrosis." (PMID 28640808, 2017). "In cystic fibrosis [CF], the absence of functional cystic fibrosis transmembrane regulator channel (CFTR) upregulates the ENaC channel activity and further decreases salt and water secretion by reabsorbing sodium ions." (PMID 27073804, 2016). "Although these studies have provided insights into cystic fibrosis pathology from high-throughput approaches, it should be noted that the testis, which produces sperm, has a unique environment for CFTR function." (PMID 27483469, 2016). "The data reported here provide the first proof of concept that repeated administration of non-viral CFTR gene therapy can safely change clinically relevant parameters, providing another step along the path of translational cystic fibrosis gene therapy." (PMID 26149841, 2015). "In BHK cells expressing the ΔF508 CFTR mutant (CFTRΔF508), the most common mutation causing cystic fibrosis, both S1P receptor antagonism and AMPK inhibition enhance CFTR activity, without instigating discernable correction." (PMID 26079370, 2015). "Under pathological conditions such as cystic fibrosis and similar diseases, the activity of MLK3 and other core pathways can become deleterious, as it enhances the degradation of protein mutants that retain the potential to function (such as F508del-CFTR)." (PMID 26701908, 2015). "In an animal model of cystic fibrosis, with the lack of cystic fibrosis transmembrane conductance regulator (CFTR), alveolar fluid clearance was decreased." (PMID 26640323, 2015). "Osthole has also been suggested as a natural activator of defective DeltaF508-cystic fibrosis transmembrane conductance regulator (CFTR) chloride channel gating and thus may be a lead compound for cystic fibrosis therapies." (PMID 26246843, 2015). "Working with bronchial epithelial cells from cystic fibrosis patients, the authors checked whether triggering the HSR (by heat-shocking the cells) would exacerbate the mutant CFTR trapping." (PMID 25405339, 2014). "To determine whether this regulation occurs in bronchial epithelial cells from cystic fibrosis patients (CFBE41o-, referred to as CFBE), we treated CFBE-WTCFTR cells (CFBE cells stably transfected with CFTR) with IGF-1." (PMID 23555857, 2013). "Despite identification of the cystic fibrosis transmembrane conductance regulator (CFTR) anion channel as the causative gene for CF and having a mouse model where CFTR has been disrupted, for over 20 years, little advancement has been made in the understanding of CF." (PMID 23151353, 2012).
cystic fibrosis (continued). "Dexamethasone is widely used for pulmonary exacerbation in patients with cystic fibrosis, however, not much is known about the effects of glucocorticoids on the wild-type cystic fibrosis channel transmembrane regulator (CFTR)." (PMID 23272037, 2012). "Despite the broad distribution, the role of CFTR in the kidney remains uncertain as there is no major disruption of renal function in cystic fibrosis patients, apart from a reduced renal excretion of NaCl." (PMID 23284854, 2012). "Delivery of viral vectors to patients with cystic fibrosis is inefficient and even when successfully delivered, the resultant normal CFTR expression is only transient and does not result in long-term functional improvement." (PMID 23029546, 2012). "In cystic fibrosis, other genes are required to explain the clinical heterogeneity with the extent of liver and lung involvement not explained by CFTR alone." (PMID 21545724, 2011). "We speculate that YKL-40 levels in CF reflect the extent of neutrophilic airway inflammation rather than being modulated directly by the genetic CF defect (Cystic Fibrosis Transmembrane Conductance, CFTR)." (PMID 21949714, 2011). "The absence of a functional ABC protein, CFTR, from apical membranes of epithelial cells is the basis of this pathophysiology in cystic fibrosis." (PMID 18463704, 2008). "One of the clinical manifestations of cystic fibrosis not adequately predicted by the cystic fibrosis transmembrane conductance regulator (CFTR) genotype is the intestinal phenotype meconium ileus." (PMID 17506901, 2007). "It was proposed that polymorphisms in the MDR1 gene may have clinical consequences in patients with cystic fibrosis, since MDR1 plays a role in CFTR regulation." (PMID 15967026, 2005). "The expression of CFTR in BEST4+ cells in the large intestine may have important implications to understand epithelial fluid efflux, regulation of mucus viscosity, and for the management of cystic fibrosis or diarrheal disease." (PMID 40907661, 2026). "The assessment of cystic fibrosis transmembrane conductance regulator (CFTR) activity is essential to both diagnose and evaluate the efficacy of treatments in cystic fibrosis." (PMID 42240701, 2026). "Applied to forskolin-induced swelling assays of lung organoids, the algorithm successfully quantified functional differences in Cystic Fibrosis Transmembrane conductance Regulator (CFTR)-channel activity between healthy donor and cystic fibrosis patient-derived organoids, without fluorescent dyes." (PMID 41144388, 2025). "The ion channel-forming natural product amphotericin B (AmB) can serve as a molecular prosthetic for the cystic fibrosis transmembrane conductance regulator (CFTR) anion channel and thereby restore host defenses in cultured cystic fibrosis airway epithelia." (PMID 40909600, 2025). "We searched PubMed (Dec 15, 2023), without language restrictions using the search terms (((cystic fibrosis)) AND (“CFTR modulators” OR ivacaftor OR tezacaftor OR vanzacaftor OR elexacaftor OR deutivacaftor OR lumacaftor)) AND filter “Article type: Meta-analysis” and identified 12 results." (PMID 41377908, 2025). "Through this strategy, delivering the 5′- and 3′- halves of the cystic fibrosis transmembrane conductance regulator (CFTR) cDNA by two AAV vectors could enable the splicing of two pre-mRNAs, forming a complete and functional CFTR mRNA in human cystic fibrosis airway epithelial IB3-1 cells." (PMID 38327848, 2024). "Here, we present the case of an 8-year-old female, initially diagnosed as “CFTR-related metabolic syndrome/cystic fibrosis screen positive, inconclusive diagnosis” (CMRS/CFSPID), who then progressed to CF at 12 months." (PMID 39458368, 2024). "Since the approval of the highly effective modulator therapies (HEMT) targeting the cystic fibrosis transmembrane conductance regulator (CFTR) protein, the use of HEMT have been crucial alongside the supplementary symptomatic treatments for cystic fibrosis." (PMID 37795027, 2023).
cystic fibrosis (continued). "To study the impact of H2O2, nitrite, single, and dual infections at the epithelial cellular level in the presence and absence of a functional epithelial CFTR, we employed a cell culture model infection with 16HBE and cystic fibrosis bronchial epithelial (CFBE) cell lines." (PMID 37800950, 2023). "CRD is a nonclassical CF induced by disease-causing variants of different severity, resulting in either single or multiorgan involvement, depending on each organ's susceptibility to malfunctioning of the cystic fibrosis transmembrane conductance regulator (CFTR) protein." (PMID 36832409, 2023). "Triple combination therapy with the CFTR modulators elexacaftor (ELX), tezacaftor (TEZ) and ivacaftor (IVA) has been qualified as a game changer in cystic fibrosis." (PMID 37025483, 2023). "The introduction of the Cystic Fibrosis Transmembrane Conductance Regular (CFTR) modulator, a triple combination of elexacaftor, tezacaftor, and ivacaftor (ETI, TRIKAFTA®), has led to substantial improvements in lung function for people with cystic fibrosis (pwCF)." (PMID 37242680, 2023). "While it may play a role in modulating agonist-induced CFTR-mediated anion currents, it is not localized in the apical membrane, and it has no function as an apical anion channel in cystic fibrosis and healthy human colonic epithelium." (PMID 37762516, 2023). "In CFTR knockout mice, transient expression of a normal copy of CFTR in utero rescues lethality and some of the lung and intestinal phenotypes of cystic fibrosis even when this CFTR is no longer expressed after birth, suggesting that CFTR is particularly important during development." (PMID 35237593, 2022). "Despite high CFTR carrier burden, the variants with high carrier frequencies, c.4056G > C (p.Gln1352His) and c.1210-11T > G, are associated with congenital bilateral absence of vas deferens (CBAVD) and pancreatitis instead of cystic fibrosis." (PMID 36335097, 2022). "Combined treatment with antagomiRNAs might lead to maximized upregulation of CFTR and should be considered in the development of protocols for CFTR activation in pathological conditions in which CFTR gene expression is lacking, such as Cystic Fibrosis." (PMID 36012615, 2022). "Even with the successful development of small molecule cystic fibrosis transmembrane conductance regulator (CFTR) correctors and potentiators, there is only a modest effect on established infection and inflammation in CF patients." (PMID 34054509, 2021). "The gene responsible for CF, the CFTR (Cystic Fibrosis Transmembrane Conductance Regulator) gene, has been discovered in 1989." (PMID 33967785, 2021). "This pathological condition is clearly seen in cystic fibrosis where there may be a complete absence of CFTR function." (PMID 34680554, 2021). "For example, these cell lines lack ionocytes, a rare epithelial cell type that is the main source of the cystic fibrosis transmembrane conductance regulator (CFTR), an important component of cystic fibrosis." (PMID 34065016, 2021). "Since cystic fibrosis patients have in many cases impaired or not functional CFTR, an organoid-based assay has been developed to identify which patients are responsive to a CFTR-rescuing pharmacological therapy." (PMID 33627108, 2021). "Stalvey and co-workers assessed linear growth and weight in 83 children with cystic fibrosis, 6 to 11 y, enrolled in two clinical trials, the longitudinal, observational GOAL study and the placebo-controlled ENVISION study to evaluate the effects of ivacaftor, a CFTR potentiator." (PMID 34290673, 2021). "This trio increases the activity of the cystic fibrosis transmembrane conductance regulator (CFTR) protein and reduces the mortality and morbidity rates in CF patients." (PMID 34268058, 2021).